GIMAP6 (GTPase, IMAP family member 6)
Synonyms: IAN-2; IAN-6; IAN2; IAN6; FLJ22690
Tractability: PROTAC: ubiquitination databases record sites on it; its protein half-life has been measured.
Gene: Protein-coding gene on chromosome 7 (150,625,375 to 150,632,648, reverse strand). Ensembl gene ENSG00000133561.
Subcellular location: Cytoplasm, cytosol
Gene Ontology:
Molecular function: GTPase activity; GTP binding
Cellular component: cytosol
Genetic constraint (gnomAD): Loss-of-function variants: 8 observed, 10.36 expected, observed/expected ratio (o/e) 0.77, 90% interval 0.45 to 1.39. The upper end of that interval is the gene's LOEUF score, 1.39, which puts it in group 5 of 6, group 1 being the genes least tolerant of losing a copy. Missense variants: 329 observed, 367.8 expected, observed/expected ratio (o/e) 0.89, 90% interval 0.82 to 0.98. Synonymous variants: 154 observed, 155.79 expected, observed/expected ratio (o/e) 0.99, 90% interval 0.87 to 1.13.
Homologues: Orthologues: chimpanzee GIMAP6 (100% identical), macaque GIMAP6 (89% identical), guinea pig GIMAP6 (54% identical), rat Gimap6 (52% identical), mouse Gimap6 (51% identical). Paralogues in human: GIMAP1 (41% identical), GIMAP5 (35% identical), GIMAP2 (34% identical), GIMAP8 (33% identical), GIMAP4 (32% identical), GIMAP7 (30% identical), GIMD1 (17% identical).
Diseases named in the same sentence as GIMAP6 in open-access papers:
GIMAP6 is named in the same sentence as 17 diseases in open-access papers, as found by Europe PMC text mining. Sharing a sentence is not in itself a finding about the gene and the disease. The quoted sentences say what the papers report.
breast carcinoma (3 papers, 2022 to 2025). "GIMAP6 has been recognized as a prognostic biomarker in head and neck squamous cell carcinoma, breast cancer, and female lung adenocarcinoma and as a predictor of response to immunotherapy in lung adenocarcinoma." (PMID 35711463, 2022). "Another bioinformatic analysis on GIMAP family members indicated that GIMAP7 together with GIMAP1, GIMAP5, GIMAP6, and GIMAP8, are lowly expressed in breast cancer tissues." (PMID 38151913, 2024). "Bioinformatics show GIMAP1, GIMAP5, GIMAP6, GIMAP7, and GIMAP8 are downregulated in breast cancer." (PMID 40535419, 2025).
hepatocellular carcinoma (3 papers, 2020). A malignant tumor that arises from hepatocytes. "It was reported that the downregulation of the mRNA and protein expression levels of GIMAP5 and GIMAP6 in the tumor tissues and blood of patients with hepatocellular carcinoma." (PMID 33115964, 2020). "Decreased expression of the GIMAP6 gene has also been noted in hepatocellular carcinoma." (PMID 33552133, 2020). "That suggested GIMAP5 and GIMAP6 could involve in the pathogenesis of hepatocellular carcinoma." (PMID 33115964, 2020).
non-small cell lung carcinoma (3 papers, 2020 to 2021). A group of at least three distinct histological types of lung cancer, including non-small cell squamous cell carcinoma, adenocarcinoma, and large cell carcinoma. "Abnormal expression of GIMAP family members in cancer tissues has also been reported in non-small cell lung cancer, and qPCR analysis showed downregulation of GIMAP6 and GIMAP8 in lung cancer tissues." (PMID 33691643, 2021). "Dysregulation of GIMAP6 expression is observed in non-small cell lung cancer, where the GIMAP6 gene expression is decreased in tumor samples." (PMID 33552133, 2020).
lymphopenia (2 papers, 2009 to 2018). Reduction in the number of lymphocytes. "We similarly speculate that the peripheral T cell lymphopenia seen in the Gimap6 knock-out mice arises because of a reduction in autophagic flux leading to a failure of normal mitochondrial clearance." (PMID 29718959, 2018). "While we can exclude theinvolvement of the members of the Gimap family proximal to D4Rhw6 (Gimap8, Gimap9, Gimap4, Gimap6, and Gimap7)in the development of lymphopenia, we cannot exclude that they may play a rolein the development of T1D." (PMID 19421422, 2009).
anaplastic large cell lymphoma (1 paper, 2021). Anaplastic large cell lymphoma (ALCL) is a rare and aggressive peripheral T-cell non-Hodgkin lymphoma, belonging to the group of CD30-positive lymphoproliferative disorders, which affects lymph nodes and extranodal sites. "The expression of GIMAP5 occurs in many T cell leukemic cell lines and in anaplastic large cell lymphoma (ALCL) cell lines while the expression of GIMAP1, GIMAP2, GIMAP6 and GIMAP7 were down-regulated in ALCLs." (PMID 34135906, 2021).
asthma (1 paper, 2020). "Five novel hub DEGs (i.e., JAM2, SIGLECP3, C14orf186, COL15A1, and GIMAP6) were identified in asthma-IPF among ten hub DEGs." (PMID 31952466, 2020). "In addition, other identified genes were LRRC48 and CETN2 in asthma-COPD, COL15A1, GIMAP6, and JAM2 in asthma-IPF, along with LMO7, TSPAN13, LAMA3, and ANXA3 in COPD-IPF." (PMID 31952466, 2020). "These genes included RBM42, STX5, and TRIM41 in asthma, CYP27A1, GM2A, LGALS9, SPI1, and NLRC4 in COPD, ATF3, PPP1R15A, ZFP36, SOCS3, NAMPT, and GADD45B in IPF, LRRC48 and CETN2 in asthma-COPD, COL15A1, GIMAP6, and JAM2 in asthma-IPF and LMO7, TSPAN13, LAMA3, and ANXA3 in COPD-IPF." (PMID 31952466, 2020). "Accordingly, COL15A1, GIMAP6, and JAM2 may present a novel therapeutic strategy for the asthma-IPF." (PMID 31952466, 2020).
atherosclerosis (1 paper, 2026). A disease characterized by the build-up of fatty material and calcium deposition in the arterial wall resulting in partial or complete occlusion of the arterial lumen. "Here, we report that loss of the immunoregulatory gene GTPase of immunity-associated protein 6 (GIMAP6), causes an inflammatory vasculopathy and accelerated atherosclerosis in the absence of hyperlipidemia." (PMID 41743988, 2026).
autoimmune disease (1 paper, 2022). A disorder resulting from loss of function or tissue destruction of an organ or multiple organs, arising from humoral or cellular immune responses of the individual to their own tissue constituents. "GIMAP6 protein can act on the regulation of the activation and apoptosis of peripheral T cells to maintain the homeostasis of peripheral T cells, and the dysregulation of T-lymphocyte homeostasis is closely linked to autoimmune diseases." (PMID 35711463, 2022). "Thereby, in autoimmune diseases, GIMAP6 may promote the T-cell–mediated immune response immunity by regulating T-cell activity." (PMID 35711463, 2022).
metastatic tumors (1 paper, 2024). "Analyses of patient data from the Cancer Genome Atlas (TCGA) showed that GIMAP6, SAMD9L, and IL27 are significantly upregulated in metastatic tumors compared to the primary lesions, whereas TAP1 was not differentially expressed in patient samples." (PMID 38719996, 2024).
tumor (9 papers, 2018 to 2025). "IKZF1 is a known tumor-suppressor gene, and high GIMAP6 expression level is also associated with a favorable prognosis in patients with LUAD and LIHC." (PMID 36311703, 2022). "Overexpression of GAS6-AS1 inhibited the proliferation of LUAD cells in vitro and tumor growth in vivo by regulating miR-24-3p and GIMAP6." (PMID 34513660, 2021). "GIMAP6 was expressed at lower levels in the tumor samples with a better prognosis, which is the same with our study." (PMID 33115964, 2020). "Both TCGA and GEO data showed a good predictive value, and four genes (GIMAP6, CD80, IL16, CCR2) contributed the most to predicting tumor purity." (PMID 35280857, 2022). "We divided the 443 TCGA LUAD samples with complete clinical data into high and low groups according to tumor purity, and obtained CSGTPP (0.21*CCR2+ 0.06*GIMAP6+0.64*CD80+ 0.21*IL16) with LASSO regression analysis, and then divided the samples into high and low two groups." (PMID 35280857, 2022). "Furthermore, we obtained four genes (GIMAP6, CD80, IL16, and CCR2) that had predictive advantages for tumor purity using random forest classification and random forest regression." (PMID 35280857, 2022). "Interestingly, our data show a significant decrease in mRNA levels of GIMAP4, GIMAP6, GIMAP7 and GIMAP8 in BC tissues, compared to DCIS tissues, and non-tumor breast tissues from either women with or without BC (supplementary 2)." (PMID 32523132, 2020).
cancer (2 papers, 2019 to 2021). A tumor composed of atypical neoplastic, often pleomorphic cells that invade other tissues. "Notably, GIMAP6 had significantly higher expression levels in the lower-TMB subtype than in the higher-TMB subtype of 15 cancer types." (PMID 30634925, 2019).
infection (2 papers, 2019 to 2022). The state of being infected such as from the introduction of a foreign agent such as serum, vaccine, antigenic substance or organism. "In addition, CCR5-deficiency during infection affected the upregulation of cytokine genes such as Csf2, Csf3, Cxcl1, Edn1, and Il6 and other genes associated with immune response (i.e., Gimap6, Mcoln2) and migration (i.e., Cyfip2)." (PMID 31506064, 2019). "In contrast to myeloid cells, DCs, and ECs, we only detected few transcripts that are significantly elevated with infection in T cells including B2m, Satb1, Gm42418, Gimap6 in CD4+ T cells and Gm42418 in CD8+ T cells." (PMID 35789215, 2022).
cardiovascular disease (1 paper, 2026). "In humans, rare deleterious GIMAP6 variants are associated with premature severe cardiovascular disease." (PMID 41743988, 2026).
GIMAP6 also shares sentences with these, for which no sentence is quoted: lung adenocarcinoma (2 papers); head and neck squamous cell carcinoma (1); hyperlipidemia (1); lung carcinoma (1).